TF (transferrin)
Diseases named in the same sentence as TF in open-access papers (continued):
Sharing a sentence is not in itself a finding about the gene and the disease.
iron deficiency (continued). "The laboratory diagnosis of absolute iron deficiency has been based on low serum iron, low percent transferrin saturation (TSAT), and low ferritin." (PMID 23555091, 2013). "Iron deficiency anaemia was identified in seven of the anaemic participants who simultaneously had serum ferritin and/or transferrin saturation below normal range." (PMID 23861932, 2013). "This is because a patient with an increased serum transferrin level often suffers from iron deficiency anaemia." (PMID 23978045, 2013). "Transferrin saturation and iron are normal and indeed phlebotomy rapidly induces iron deficiency anaemia." (PMID 24368960, 2013). "Iron deficiency (transferrin saturation (TSAT) < 20% and ferritin < 100 ng/ml) was seen in 14.9% patients, its incidence being highest in stage 4 patients." (PMID 23865418, 2013). "It is also evident that during BT, SF soldiers developed iron deficiency and anemia symptoms associated with 39% low transferrin saturation (< 16%), 36.4% ferritin deficiency (< 20 ng/ml), and 37.9% hemoglobin deficiency (< 14 g/dl)." (PMID 22413851, 2012). "In 31 (34%) of all patients with anemia, values of iron, ferritin, and transferrin saturation had been measured; in another 32 patients, an iron-deficiency anemia was diagnosed due to microcytosis and CRP levels." (PMID 22899905, 2012). "This reflects the systemic iron deficiency of these animals when compared to their uninfected counterparts, as they have reduced circulating iron loaded onto the transferrin protein." (PMID 23185574, 2012). "In half cases, iron deficiency is absolute (with low transferrin saturation and serum ferritin, usually associated with decreased iron stores and reduced iron deposits in the bone marrow)." (PMID 22536520, 2012). "In the other half cases iron deficiency is functional-relative (with low transferrin saturation and normal or elevated serum ferritin, usually associated with normal or elevated iron stores and iron deposits in the bone marrow)." (PMID 22536520, 2012). "The mechanism by which TF overcomes the dual challenges of iron deficiency and overload in cells is via a TF/TF receptor (TFR)-mediated endocytotic process." (PMID 23194296, 2012). "The Auerbach trial in 2004 probably included patients with an absolute iron deficiency since one inclusion criterion was ferritin ≤200 μg/L or <300 μg/L with transferrin saturation ≤19%." (PMID 22111015, 2011). "Total iron binding capacity measures the blood's capacity to bind iron with transferrin, and values are expected to be higher in individuals with iron deficiency, compared to those who are iron replete." (PMID 21483845, 2011). "Considering that transferrin saturation is a marker of the iron supply to tissues, A carriers present a reduction in iron transport to tissues, as occurs in iron deficiency anaemia." (PMID 21978626, 2011). "Iron deficiency resolved with symptoms (posttreatment serum iron 184 μg/dL, transferrin saturation percentage 49.3%)." (PMID 20798868, 2010). "Iron deficiency was in turn defined as having at least two of the following: transferrin saturation less than 15%, serum ferritin less than 12 ng/mL, or erythrocyte protoporphyrin concentration greater than 1.24 uM." (PMID 20368776, 2010). "Of anaemic women, 50.0% had a transferrin saturation less than 10% indicating iron deficiency, 34.5% were deficient in B12 vitamin and 71.7% were deficient in folate." (PMID 20537176, 2010). "While further experimentation is necessary, these findings suggest that iron deficiency results in ineffective erythropoiesis as a consequence of relatively insufficient circulating transferrin to accommodate the degree of erythropoiesis." (PMID 20631898, 2010). "The importance of the transferrin pathway in brain uptake of Mn is underscored by observations of increased Mn levels in the brains of rats following iron deficiency, which up-regulates transferrin-mediated transport." (PMID 19337503, 2009).
iron deficiency (continued). "We employed the parameters such as serum iron, TIBC and transferrin for detection of iron deficiency and transferrin saturation and serum ferritin for iron depletion." (PMID 20041071, 2008). "In a study in Niger, S. haematobium egg count and intensity of haematuria were negatively correlated to haemoglobin level, to haematocrit and to transferrin saturation, and positively associated with anaemia and iron deficiency." (PMID 18509472, 2008). "In summary, utilizing a unique GeneChip® dataset and a variety of computational approaches has allowed us to predict that some genes important for the response to iron-deficiency in the rodent intestine are transcriptionally regulated by SP1 or a related TF." (PMID 18005439, 2007). "Iron deficiency was defined as the presence of ≥2 of the following: low ferritin, low transferrin saturation or high erythrocyte protoporphyrin." (PMID 16300683, 2005). "Iron deficiency was defined as transferrin saturation (TSAT) below 20%." (PMID 41543817, 2026). "Iron deficiency was defined as a transferrin saturation (TSAT) below 20 %." (PMID 41631034, 2026). "However, its invasive nature has led to the use of various blood parameters, including serum iron, serum ferritin, transferrin saturation, and reticulocyte hemoglobin content, to diagnose iron deficiency." (PMID 40218414, 2025). "The concurrent increase in transferrin and iron levels indicates enhanced iron transport capacity, which could be beneficial in conditions such as iron deficiency anemia." (PMID 41172682, 2025). "Therefore, we recommend that further studies to consider the evaluation of iron deficiencies anemia indicators like serum ferritin, and serum transferrin, as well as serum folate and serum Vit-B12." (PMID 39792710, 2025). "For instance, some analyses indicate patients with more severe iron deficiency (transferrin saturation <20%) derive the greatest benefit, whereas those with only borderline low ferritin might see less impact." (PMID 40910148, 2025). "Iron deficiency may predominate, with reduced ferritin or transferrin/iron saturation levels; however, it should be remembered that ferritin is often artefactually elevated in patients with raised alcohol consumption." (PMID 39780754, 2025). "Approximately 30% to 50% of anemic patients presenting for cardiac surgery have absolute iron deficiency with depleted iron stores, mainly indicated by low serum ferritin (<100 ng/mL), low transferrin saturation (<20%), and low reticulocyte count due to different pathomechanisms." (PMID 41303295, 2025). "Functional iron deficiency, with high ferritin but low transferrin saturation, could reduce iron bioavailability for fetal oxygenation, potentially causing fetal hypoxia and growth impairment." (PMID 41470856, 2025). "Although a variety of definitions are used incorporating different cutoffs of multiple laboratory parameters, perioperative iron deficiency is commonly defined as either a ferritin level <100 μg/L or a ferritin level <300 μg/L in combination with transferrin saturation <20%." (PMID 41303295, 2025). "Furthermore, the observed increases in RBC count, hematocrit levels, and transferrin saturation further support the clinical efficacy of both supplementation approaches in correcting iron deficiency." (PMID 41287676, 2025). "Clinical studies have shown that patients with CRC often exhibit a functional iron deficiency—characterized by low serum iron and % transferrin saturation despite preserved or elevated ferritin levels—but the implications of these changes in tumor biology remain largely unexplored." (PMID 40507970, 2025). "This study aims to assess the clinical utility of Ret-Hb measurement in patients undergoing chronic hemodialysis and to compare its performance with conventional biochemical markers of iron metabolism (serum ferritin, serum iron, transferrin) in the diagnosis of iron deficiency." (PMID 40497187, 2025).
iron deficiency (continued). "However, distinguishing between ferritin's role as an acute-phase reactant and true iron deficiency requires additional biomarkers, such as transferrin saturation or soluble transferrin receptor levels, which were not evaluated in this study." (PMID 40698207, 2025). "The determination of transferrin (TF) levels is used in the differential diagnosis of iron-deficiency anemias, characterized by decreased serum iron content, an increase in the level of this glycoprotein, and consequently, a decrease in the percentage of transferrin saturation with iron." (PMID 38612266, 2024). "Two HFE SNPs (rs1800562 and rs1799945) and one TF SNP (rs1799852) exhibited protective effects, while the other 11 SNPs were linked to increased risk of iron deficiency, suggesting potential benefits from iron supplementation for individuals with those genetic variants." (PMID 39599580, 2024). "An increase in transferrin concentration is a sign of iron deficiency." (PMID 38590521, 2024). "Our findings with the association between the three measures of iron deficiency and depression may differ due to the different functions of ferritin, serum iron, and transferrin." (PMID 38226328, 2024). "Therefore, we investigated the association between iron deficiency and cardiovascular events during long-acting erythropoiesis-stimulating agent therapy using transferrin saturation (TSAT), which is less susceptible to inflammation than ferritin." (PMID 38941000, 2024). "In this study, the inverse association of serum iron and transferrin saturation with MASLD mortality may represent the effect of iron deficiency on MASLD." (PMID 39464186, 2024). "This was a post hoc exploratory analysis of the IRONMAN trial which randomized patients with heart failure, a left ventricular ejection fraction (LVEF) ≤ 45% and iron deficiency (transferrin saturation <20% or ferritin <100 μg/L) to open label intravenous ferric derisomaltose or usual care." (PMID 38549192, 2024). "In our reverse direction MR analysis that utilized DN as the exposure and iron status as the outcome, we found that DN was genetically associated with low serum transferrin concentration and low transferrin saturation level, suggesting that DN increases the risk of iron deficiency." (PMID 39054539, 2024). "Although it has been established that patients with chronic kidney disease and iron deficiency, as indicated by a transferrin saturation of < 20%, are at increased risk of all-cause mortality and cardiovascular events, the optimal management of such patients has not yet been determined." (PMID 39229929, 2024). "This increase in transferrin production may be an effort to optimize iron absorption and maintain homeostasis in the face of iron deficiency." (PMID 39600914, 2024). "In the present study, the significantly elevated serum transferrin levels observed in the aerobic group are speculated to reflect the body's attempt to compensate for the higher prevalence of iron deficiency anemia in this group." (PMID 39600914, 2024). "Although the exact mechanism is unknown, iron deficiency has been suggested to lead to a hypercoagulable state and increased risk of thrombosis, either through thrombocytosis or by increasing transferrin expression as well as estrogen." (PMID 38941000, 2024). "By avoiding both iron deficiency and overload, moderate transferrin saturation might optimize cellular function and minimize oxidative stress." (PMID 39796572, 2024). "In line with the latest ESPEN guideline, treatment for iron deficiency should be initiated based on a comprehensive evaluation of iron status including plasma iron, transferrin, transferrin saturation, ferritin, C-reactive proteins, hepcidin, and red blood cell morphology." (PMID 38999801, 2024).
iron deficiency (continued). "A biochemical profile consistent with iron deficiency (low ferritin and transferrin saturation) occurred more frequently during follow‐up in patients randomized to dapagliflozin, consistent with an increased iron demand due to stimulation of erythropoiesis by SGLT2 inhibitors." (PMID 38549192, 2024). "Thirdly, we assessed iron deficiency by measurement of transferrin saturation." (PMID 39239538, 2024). "Serum transferrin concentration increases with iron deficiency." (PMID 39797144, 2024). "In such cases, low transferrin saturation and low ferritin levels could support a diagnosis of iron deficiency, especially if patients suffer from a chronic condition." (PMID 38399784, 2024). "Transferrin has also been a factor in the modulation of adipocyte differentiation, as the administration of transferrin improved the attenuation in adipogenesis caused by iron deficiency, and in the modulation of iron overload, as increasing serum transferrin reduced tissue iron accumulation." (PMID 36902180, 2023). "In addition, the local trust guideline was to undergo revision to include screening of HF patients for iron deficiency and the creation of a laboratory HF request bundle that will include ferritin and transferrin saturation." (PMID 37965394, 2023). "An elevated transferrin level or TIBC is a marker of iron deficiency; a reduced transferrin / TIBC may occur in the context of an acute phase reaction, chronic disease, or iron overload." (PMID 36823529, 2023). "The patients were divided into four groups according to their transferrin saturation rate and serum ferritin levels: Group 1 (n = 34,539, normal iron status); Group 2 (n = 4476, absolute iron deficiency); Group 3 (n = 1719, functional iron deficiency); Group 4 (n = 1656, high iron status)." (PMID 37299540, 2023). "Furthermore, treatment with SGLT2 inhibitors leads invariably to a decrease in serum ferritin and transferrin saturation in laboratory findings that meet the typical current diagnostic criteria for an ensuing iron deficiency." (PMID 38137939, 2023). "Hepatic disease can also result in functional iron deficiency associated with altered transferrin metabolism, which might explain the predominance of elliptocytes in some goats." (PMID 37662982, 2023). "The data illustrate several key parameters used to identify iron deficiency, including serum ferritin levels at an average of 45.6 ng/mL with a standard deviation of ±12.4, transferrin saturation percentages at 20.3 ± 5.7, MCV at 82.4 ± 3.2 fL, and RDW at 13.1 ± 1.8%." (PMID 38149144, 2023). "In this report, we explored the association between LRG1 and anemia in children by assessing the correlation between LRG1 and several iron deficiency markers, including hemoglobin, iron, percentage of transferrin saturation, ferritin, albumin, and red cell distribution width (RDW)." (PMID 37513518, 2023). "Vaccine effectiveness was assessed in terms of incidence rates of SARS-CoV-2 infection confirmed by real-time polymerase chain reaction assay, relative risks of COVID-19–related hospitalization, and mortality in individuals with iron deficiency (ferritin <30 ng/mL or transferrin saturation <20%)." (PMID 37216375, 2023). "Iron deficiency can manifest in cancer patients as either absolute iron deficiency, characterized by low levels of ferritin in conjunction with reduced transferrin saturation, or more commonly, as functional iron deficiency with normal or high levels of ferritin." (PMID 37999123, 2023). "However, serum iron and transferrin saturation values indicate that insufficient iron intake and resulting iron deficiency occur not only in women, but also in men of all three groups." (PMID 38017527, 2023). "However, in the context of HF and CKD, the diagnostic criteria for iron deficiency are more stringent, with a ferritin level of less than 100 μg/L or a transferrin saturation (TSAT) of 20% or less when serum ferritin is below 300 μg/L." (PMID 38137939, 2023).
iron deficiency (continued). "We found significant linear relationships of age with ferritin and transferrin, which emphasize the importance of adjusting for age when studying iron markers and may contribute to better clinical criteria for iron overload and iron deficiency." (PMID 36091521, 2022). "Notably, a ferritin level of less than 100 ug/L, or a combination of a ferritin level between 100 and 299 ug/L and transferrin saturation under 20%, are now guideline-recommended cut-offs for diagnosing iron deficiency in patients with heart failure." (PMID 35508964, 2022). "Furthermore, alcohol use can lead to either iron deficiency or excessively high levels of iron in the body especially in the liver concomitantly causing transferrin loss that enhances absorption of iron." (PMID 35377899, 2022). "The assessment of iron deficiency is complicated by the fact that iron parameters such as ferritin, transferrin saturation, and zinc protoporphyrin are affected in any infectious or inflammatory process, with the presence of (low-grade) inflammation leading to an underestimation of iron deficiency." (PMID 36698466, 2022). "Transferrin saturation of <15–20% is considered indicative of iron deficiency." (PMID 35807896, 2022). "The trial was a Phase 2, double-blind, placebo-controlled randomized clinical trial with 225 participants that defined heart failure as LVEF< 40% and iron deficiency as serum ferritin level between 15-100 ng/ml or serum ferritin 101-299 ng/ml with transferrin saturation (TSAT) <20%." (PMID 36017290, 2022). "ROX improves iron utilization parameters by decreasing ferritin, TSAT, and hepcidin and increasing TIBC and transferrin, thus enhancing the utilization of iron in the body; this may lead to iron deficiency." (PMID 35363823, 2022). "In addition, heart failure patients with LVEF < 50% should be considered for iron supplementation if iron deficiency is diagnosed (ferritin < 100 ng/mL or ferritin 100–299 ng/mL with transferrin saturation < 20%)." (PMID 35204567, 2022). "Both Sucrosomial® iron and ferrous sulfate were able to overcome the effects of iron deficiency as indicated by significant increases in liver iron concentration, serum iron levels, transferrin saturation, red blood cell count, hemoglobin, hematocrit and mean corpuscular volume." (PMID 34697758, 2022). "Interestingly, in some ALD cases, serum iron parameters were low without overt iron deficiency anemia, where the criteria for iron deficiency anemia was “(serum ferritin < 20 μg/L, hemoglobin < 11 g/dL, and transferrin saturation < 16%)”." (PMID 36214835, 2022). "However, there are other biomarkers that are specific to the diagnosis of iron deficiency anemia, such as Transferrin and Ferritin." (PMID 36315485, 2022). "It is suggested that transferrin saturation could also serve as an effective diagnostic criterion for iron deficiency." (PMID 36407516, 2022). "The trial included 1,108 patients with LVEF< 50% after receiving at least 40 mg IV furosemide (or similar) and having indications of iron deficiency (serum ferritin <100 ng/mL or ferritin 100-299 ng/mL with transferrin saturation <20%) after initial clinical stabilization." (PMID 36017290, 2022). "Taken together, our findings highlight that elevation of serum transferrin level might be associated with a high risk of autism, suggesting a potential role of iron deficiency in autism development." (PMID 36407516, 2022). "Moreover, in one vegetarian and one vegan only transferrin saturation was below 16%, indicating latent iron deficiency." (PMID 35651513, 2022). "Thus, data analysis showed that low transferrin levels in females with ovarian cancer are associated with functional iron deficiency, CRA and advanced stages of the disease." (PMID 36555993, 2022). "Besides, studies have suggested that serum transferrin can be a useful indicator for diagnosis of iron deficiency anemia, highly sensitive and specific in nature." (PMID 36451738, 2022).